CD8B (CD8 subunit beta)
Diseases named in the same sentence as CD8B in open-access papers (continued):
Sharing a sentence is not in itself a finding about the gene and the disease.
tumor (continued). "CD8+ T cell abundance was quantified from tumor RNAseq profiles using a four-gene expression signature score (referred to as TSIG) derived from the geometric mean of the normalized log2 read counts for the genes CD8A, CD8B, CD3D, and CD3E." (PMID 32117236, 2020). "Tumor regression in response to combination treatments correlated strongly with elevated tumor expression of CD8b, Ifng, Tnfa, Ccl5 and Il18 in the non-injected tumors." (PMID 31921384, 2019). "The percentages of CD4+, CD8β+, and perforin+CD8β+ T cells in peripheral blood did not reveal any difference between tumor bearing and non-tumor bearing pigs." (PMID 29930558, 2018). "Eight days after challenge, Luc-DC were cleared from WT and CD4-depleted C57BL/6 mice, whereas CD8β-depleted mice failed to eliminate the MuTuDC lines leading to tumor outgrowth." (PMID 25101081, 2014). "In CD8β-depleted mice, we speculate that newly developed CTL were rendered tolerant in vivo and therefore were unable to control tumor growth as already described in a sporadic tumor model." (PMID 25101081, 2014). "By concomitantly adding either CD8β-depleting or CXCR3-blocking antibodies to triple treatment, we found that both CD8+ and CXCR3+ cells were crucial for the abscopal effect as adding these antibodies completely attenuated abscopal tumor control and significantly worsened mouse survival." (PMID 37045833, 2023). "To investigate whether the reduced tumor growth in GPR182−/− mice was due to improved antitumor T cell response, we depleted CD4+ and CD8+ T cells in GPR182−/− and WT mice by intraperitoneal injection of anti-CD4 and anti-CD8β depleting mAbs together." (PMID 35013216, 2022). "In tumor patients with a relatively high level of neutrophils, T cell immune response is often reduced, as represented by the reduced expression of cytotoxic T cell genes including CD8A, CD8B, GZMA, and GZMB, the reduced number of CD3 + CD8 + cells, and the reduced expression of IFN-γ related genes." (PMID 36275807, 2022). "Finally, 8 genes related to anti-tumor immunity were obtained, which were APOL3, CCL5, CD8A, CD8B, CXCL9, GZMA, GZMK and PRF1.We found that the m6A regulatory factors YTHDC1, YTHDC2, and WTAP were positively correlated with m6A, while IGF2BP3 was negatively correlated." (PMID 34737950, 2021). "Approximately four weeks after cell line challenge, tumours continued to grow in the majority of mice depleted of CD8β+ T cells or TCRβ+ T cells, but not in mice depleted of CD4+ T cells, suggesting that CD8+ T cells also play a vital role in the prevention of SCC tumour progression." (PMID 33925140, 2021). "LUAD was the only tumor type that the z-score was negative for both CD8a and CD8b." (PMID 30926812, 2019). "While a significant increase in percentage of CD8β+ T cells was found at the tumor site (mean values: 39.7% in contrast to 13.3% for the PBMC samples), the proportion of CD4+ T cells expressing the CD8α+ activation molecule was significantly reduced within tumor isolates." (PMID 29930558, 2018).
infection (43 papers, 2006 to 2025). The state of being infected such as from the introduction of a foreign agent such as serum, vaccine, antigenic substance or organism. "In previous studies using this infection model we did not detect altered expression of CTL associated genes or signs of activation of CD8β-expressing cell populations in caecal mucosa during this phase of infection of naïve chickens, which is in line with the present observations." (PMID 34521339, 2021). "However, the findings of the present study indicate that there are different expressions of TLRs, CD4, CD8b, and cytokines in these captive koala populations, which might be associated with different KoRV subtype infections." (PMID 36015032, 2022). "Further, CD8β depletion via antibody infusion is capable of disrupting the control of infections in other disease models." (PMID 39912921, 2025). "H3N2-specific CD8β+ T cells mainly expressed IFN-γ after the single infection, and the frequency peaked at 14 dpi (mean of 0.17%)." (PMID 37287962, 2023). "Nevertheless, recent research has demonstrated that during late gestation CD8αposCD27dim early effector CD8β+ T cells exhibit the strongest response to infection with the two PRRSV-1 strains compared to other investigated lymphocyte subsets." (PMID 37409113, 2023). "After challenge, macaques in Group A were also treated with anti-CD8β depleting antibody at 17 weeks post-infection (wpi) and received pRhPD1-p27 revaccination at 103 wpi." (PMID 37921496, 2023). "Consistent with IFN-γ ELISpot assay results, the frequencies of IFN-γ, TNF, and IL-2 single, double, and triple producers within the CD4+ and CD8β+ T-cell subsets were overall low after H3N2 single infection (mean < 0.5%)." (PMID 37287962, 2023). "PRRSV-2-specific CD8β+ T cells were mainly IFN-γ or IL-2 or double IFN-γ/IL-2 producers after the single infection." (PMID 37287962, 2023). "Compared to the other investigated lymphocyte subsets, CD8αposCD27dim early effector CD8β T cells showed the strongest response to infection with the two PRRSV-1 strains." (PMID 36426366, 2022). "Because CD4 and CD8 T cells also play an important role in adaptive immune responses, we assessed changes in the CNS levels of Cd4, Cd8a, and Cd8b mRNAs after infection as indicators of T cell infiltration and retention." (PMID 32047134, 2020). "After Con-A stimulation, the fold change in CD4:CD8b ratio (vs. unstimulated PBMCs) was markedly increased in one koala with endogenous infection only (H6; KoRV-A positive) and one koala positive for both exogenous subtypes (H7; KoRV-A, -B, and -C positive)." (PMID 33316950, 2020). "At day 12 post infection, the observed increase in gene expression of CD8a, CD8b, and FasL mRNA indicates that the cytotoxic T cell pathway was upregulated in the colon of Cr-infected mice." (PMID 32230738, 2020). "The expression of cytotoxic T cell markers CD8a, CD8b, and FasL mRNA were upregulated by the infection with Cr in colonic tissue." (PMID 32230738, 2020). "PD-L1-/- mice were either injected with anti-CD8β or anti-CD4 depleting mAbs or PBS prior to infection with Py, and 9, 12, and 15 days post-infection, mice received anti-LAG-3 or control isotype Abs." (PMID 33519801, 2020). "Peptide-SLA-I tetramer staining was then performed and demonstrated large responses to epitopes IAYERMCNI and DFEREGYSL at 14 days post infection, with 2.64% and 4.59% of CD8β T-cells staining positive for each of these epitopes, respectively." (PMID 29772011, 2018). "The lower expression of cd4-1, cd4-2, cd8α and cd8β in head kidney and the increased expression of the same genes in anterior intestine indicate that both TH cells and CTLs were modulated during the infection." (PMID 30064468, 2018). "Three out of six animals showed a strong increase of Ki-67+perforin+ CD8β+ T cells in blood one week post infection." (PMID 25971313, 2015).
infection (continued). "By gating on CD27dim/-perforin+ and CD27highperforin− Ki-67+CD8β+ T cells, we distinguished perforin− and perforin+ CD8β+ T cells and calculated absolute numbers in the time course following infection." (PMID 25971313, 2015). "Animals #6 and #8 showed the highest frequency of FLUAVsw-specific multifunctional cells within CD8β+ T cells, isolated at six weeks after primary infection, i.e. two weeks after secondary infection." (PMID 25971313, 2015). "Exemplary contour plots displaying all possible IFN-γ/TNF-α/CD107a/proliferation-marker combinations of gated CD8β+ T cells are shown for one control animal (#3) and one infected animal (#8) at six weeks after primary infection." (PMID 25971313, 2015). "The transcript abundance of costimulatory molecules (such as CD86, ICOS), CAMs, and TCRs/CD3 complex as well as co-receptor molecules (such as CD8A, CD8B) was remarkably increased after infection with N-PRRSV." (PMID 20614006, 2010). "Kb−/−xDb−/−xCD1d−/− mice were either mock treated or treated with a CD8β+ cell–depleting antibody during infection." (PMID 16733540, 2006). "In addition, H3N2-specific CD8β+ T cell IL-2 responses were also induced in this group, reaching 0.13% 14 dpi and then gradually declining over the course of infection." (PMID 37287962, 2023). "Both anti-CD8 groups in infection and anti-CD8β with immunization show similar localization to what has been reported previously for the primary response of endogenous CD8+ T cells against Listeria monocytogenes and the response of gBT-transgenic T cells against lymphocytic choriomeningitis virus." (PMID 30735510, 2019). "This might indicate an infection-related expansion of CD8β+ T cells in at least three (#6, #8 and #9) out of six animals." (PMID 25971313, 2015). "In our study, we could identify a clear expansion of CD8β+Ki-67+perforin+ T cells at one week after primary infection in three out of six animals." (PMID 25971313, 2015). "CD8α+ and CD8β+ cells were increased in the infected groups throughout the infection experiment; however, the cell counts were significantly higher, for both subpopulations, in the S. Virchow infected group compared to the S. Typhimurium infected group and the uninfected group at 11 DPI (P < 0.036)." (PMID 26664914, 2014). "Interestingly, despite the deficiency in the CD8α chain in CD8α−/− mice, we were able to detect an increase in CD8β mRNA production at later stages of infection versus the level in uninfected CD8α−/− mice." (PMID 21629771, 2011). "To ascertain the infection status of these monkeys, we depleted their CD8+ T cells through intravenous infusion of the anti-CD8β mAb CD8b255R1, which specifically targets macaque CD8+ T cells." (PMID 39198422, 2024). "Cr infection induced up-regulation of CD8+ T cell markers such as Cd8a, Cd8b, and FasL, suggesting involvement of CD8-mediated pathways in Cr infection." (PMID 33076301, 2020). "To evaluate variations in immune response according to KoRV subtype infection status, we measured expression levels for CD4, CD8b, IL-6, IL-10, and IL-17A in RNA isolated from unstimulated koala PBMCs." (PMID 33316950, 2020). "In the context of infection, OT1 T cells treated with anti-CD8β downregulated IL-7Rα similarly, but anti-CD8α treated did not." (PMID 30735510, 2019). "Surprisingly, the majority (> 65%) of IL-10gfp+ skin cells on day 6 post-recombinant vaccinia virus (rVV)-infection of TIGER mice were CD8+ T cells, as defined by the cell-surface markers CD45, CD8α, and CD8β." (PMID 26991092, 2016). "As a first attempt to analyze the role of T cells in the control of FLUAVsw infection, we looked for expansion of CD4 and CD8β effector T cells via analysis of Ki-67 expression." (PMID 25971313, 2015). "After S. Virchow infection, numbers of CD4+, CD8α+, and CD8β+ cells had increased in the ileum by five DPI, indicating a T helper and a cytotoxic T cell response had occurred." (PMID 26664914, 2014).
infection (continued). "Further, CD8β and IFN-γ mRNA expression in the liver coincides with a decline in viral titer, even in the hosts with a chronically evolving course of infection." (PMID 24936203, 2014). "For adaptive immune-related genes, neither cd8b nor migd expression varied across the post-infection time points." (PMID 41256851, 2025). "We then performed a similar analysis of various organs (liver, spleen and peripheral LNs) of C57BL/6 (B6) mice at day 5 after infection with Plasmodium berghei ANKA sporozoites and, similarly, detected three subsets of γδ T cells based on CD8α versus CD8β expression." (PMID 38802512, 2024). "A similar phenomenon was found when CD8β+ perforin+ double positive T cells increased when non-immune and immunized pigs were challenged with virulent infection." (PMID 34835070, 2021). "CD4 and CD8b showed no significant variation between infection subtype profiles in mRNA expression in unstimulated koala PBMCs." (PMID 33316950, 2020). "The proportion of CD4, CD8, and γδ T cells did not change significantly over the time course of H1N1pdm09 infection, although an increase in the proportion of CD8β in the BAL for the BM animals was observed, as previously reported." (PMID 33603740, 2020). "Taking into account the rapid clearance of FLUAVsw infections, we hypothesized that highly differentiated CD4+ and CD8β+ T cells with multiple effector functions are involved in protective immune responses." (PMID 25971313, 2015). "Having observed typical clinical signs of FLUAVsw infection, indicative of active viral replication in the upper and lower respiratory tract, we expected to see a FLUAVsw-specific activation of MHC-I-restricted CD8β+ T cells in infected pigs." (PMID 25971313, 2015). "In addition, mRNA analyses showed that the expression of CD8β and IFN-γ increases in the liver at 8–12 weeks after infection." (PMID 24936203, 2014). "In one study using the intraperitoneal infection route one of twelve cell lines was CD4- CD8α+ but this lacked expression of CD8β." (PMID 21573129, 2011). "Infection elicited an increase in specific IgA, IgG, and IgM antibodies and relative quantitative changes in several leukocyte populations, including CD3, CD4, CD8α, CD8β, MHC II, KuL01, and γδ TCR positive cells, both in the gastrointestinal tract and systemically." (PMID 26664914, 2014). "However, following the second infection, no increase of Ki-67+CD8β+ T cells could be detected in these three animals, and only a slight increase was found in animals #4 and #7." (PMID 25971313, 2015). "Additionally, swIAV infection also led to an increase of cells represented by cluster 10 which consisted of CD3+ T cells that were negative for CD4, CD8β and TCR-γδ, but CD2+CD8α+perforindim." (PMID 40484956, 2025). "For CD8β+ cells in the liver, hardly any IFN-γ-producing cells were identified (IFN-γ+ cells ranged from 0 to 0.1%), regardless of the type of in vitro stimulation, treatment of the birds and time point of isolation post-infection (data not shown)." (PMID 31806018, 2019).
cancer (16 papers, 2018 to 2025). A tumor composed of atypical neoplastic, often pleomorphic cells that invade other tissues. "To detect the logarithm fold change (logFC) in the expression of the four genes TCF7, LEF1, CD8A, and CD8B in different cancers, we investigated the transcriptomic profiles retrieved from the TCGA database." (PMID 35588138, 2022). "Both T cell markers (PD-1, CD8A, and CD8B) and immune checkpoint blockade PD-L1 show increased expression in samples with SCMs compared to samples without SCMs, indicating alternative splice forms induced by SCMs increase the overall immunogenicity of these cancers." (PMID 29617666, 2018). "GSCALite was utilized to identify the SNV frequency of all 6 genes (CD68, MRC1, CD8A, CD8B, CD163, and CLEC5A) in various cancers." (PMID 35979347, 2022). "Next, we evaluated the correlation between the DNA methylation and mRNA expression of CLEC5A and immune-related gene (MRC1, CD163, CD8A, CD8B, CD68) in pan-cancer." (PMID 35979347, 2022). "The pie chart showed that the heterozygous CNVs of all 6 genes (CD68, MRC1, CD8A, CD8B, CD163, and CLEC5A) was more frequent in various cancers." (PMID 35979347, 2022). "This study aimed to establish a novel four‐gene signature (CD8A, CD8B, TCF7, and LEF1) to provide a prognostic immunotherapy biomarker for different cancers." (PMID 35588138, 2022). "In the gene co‐expression network, we observed that YRDC was associated with the expression of multiple immune cell signature genes at the pan‐cancer level, including T‐cell signature genes (CD3D, CD4, CD8A, CD8B), B‐cell signature genes (CD19, MS4A1), and multiple immunoglobulin genes." (PMID 40898423, 2025). "Interestingly, CD8A, CD8B, TCF7, and LEF1 cannot serve as therapeutic targets for these cancers because of their different expression profiles." (PMID 35588138, 2022). "Thus, the DNA methylation differences of CLEC5A and immune-related gene (MRC1, CD163, CD8A, CD8B, CD68) between tumors and normal tissues in various cancers were evaluated with the GSCALite platform." (PMID 35979347, 2022). "Notably, CXCR3, CD8B, and ENTPD1 were identified as potent protective factors against six cancers." (PMID 38627900, 2024). "Moreover, CD8B was one of the biomarkers found to be present in more than 10% of the patients who developed an overt autoimmune response after SARS-CoV-2 infection and is one of the four-gene signature panel for a prognostic immune checkpoint blockade in different cancers." (PMID 38931955, 2024). "A rare population of NY-ESO-1-specific T cells, which we named 19305DP, expressed cell surface CD4, CD8α, and CD8β but not CD56 and recognized A*02+NY-ESO-1+ cancer cell lines in a CD4- and CD8-independent manner." (PMID 30626427, 2019).
immune dysfunction (2 papers, 2021 to 2022). "C5, which expressed CD8A and CD8B, was distinguished by elevated expression of GZMK, which has been recently described as a hallmark of immune dysfunction in inflammation." (PMID 35483355, 2022).
bacterial infection (1 paper, 2025). "To assess whether memory effector CD8+ T cells in the lung were protective or detrimental during secondary bacterial infection, we depleted CD8β+ T cells (intravenously and intratracheally) in WT and μMT mice before challenge with influenza (PR8) virus." (PMID 40493422, 2025).
CD8B also shares sentences with these, for which no sentence is quoted: B-cell lymphoma (5 papers); diffuse large B-cell lymphoma (5); Burkitt lymphoma (4); infectious disease (2); squamous cell carcinoma (2); Autoimmunity (1); breast invasive carcinoma (1); breast tumors (1); esophageal squamous cell carcinoma (1); Ewing sarcoma (1); gastric MALT lymphoma (1); glioma (1); hepatocellular carcinoma (1); Hodgkins lymphoma (1); Immunodeficiency (1); inflammatory bowel disease (1); leukemia (1); medulloblastoma (1); meningioma (1); mesothelioma (1); metastatic cancer (1); multiple sclerosis (1); neurological diseases (1); non-Hodgkin lymphoma (1); osteosarcoma (1); pancreatic cancer (1); pancreatitis (1); pneumonia (1); psoriasis (1); rectum adenocarcinoma (1).
A further 3 diseases each share a sentence with CD8B in 1 paper.